PLCG2 (phospholipase C gamma 2)
Diseases named in the same sentence as PLCG2 in open-access papers (continued):
Sharing a sentence is not in itself a finding about the gene and the disease.
Autoimmunity (17 papers, 2012 to 2025). The occurrence of an immune reaction against the organism's own cells or tissues. "Aberrant PLCG2 activity or mutations in PLCG2 gene have been linked to certain inflammatory disorders, such as autoinflammatory diseases and autoimmune conditions." (PMID 38167131, 2024). "Activating mutations in the PLCG2 gene have been shown to induce autoimmunity, inflammation, and/or inflammatory arthritis in murine models." (PMID 24690414, 2014). "A gain-of-function mutation in murine PLCg2 increased its membrane stability and lead to severe autoimmunity." (PMID 23555801, 2013). "Alternatively, PLCG2 mutations may predispose patients to autoimmunity-driven lung injury, akin to proposed autoimmune mechanisms in COPD, wherein immune cells target alveolar structures, triggering progressive destruction." (PMID 41537131, 2025). "Some studies have demonstrated that point mutations in the PLCG2 gene may be an important cause of severe spontaneous inflammation and autoimmunity." (PMID 37226082, 2023). "PLCγ2 is also a known risk factor and an important driver in a multitude of diverse disease circumstances including those with an immunological basis such as inflammation, autoimmunity, immunodeficiency, and allergy, as well as in hematological malignancies." (PMID 34157287, 2021). "PLCG2 plays an important role in immune response regulation and aberrant functioning of PLCG2 due to exon deletions or a missense mutation causes autoimmunity diseases." (PMID 26275715, 2015). "Two different gain-of-function mutations of murine PLCg2 lead to severe autoimmunity." (PMID 23555801, 2013). "A phospholipase Cγ2 (Plcg2) mutation resulted in severe spontaneous inflammation and autoimmunity." (PMID 22646813, 2012). "Conclusive genetic evidence demonstrates how important normal PLCγ2 function is to immune health, the overaction of which can lead to immunodeficiency, autoimmunity, or autoinflammation." (PMID 34157287, 2021). "Recently, whole-exome sequencing analysis on a pedigree with a dominantly inherited immunodeficiency and autoimmunity identified a causal mutation in a gene related to PLB1, the phospholipase Cγ2 (PLCG2) gene." (PMID 24520335, 2014). "Indeed, many of the somatic PLCG2 variants observed in the context of BTKi therapy overlap with those occurring in autoimmune PLCG2-associated immune dysregulation (APLAID), an inherited syndrome caused by germline gain-of-function PLCG2 variants." (PMID 40555733, 2025). "Mutations in the phospholipase C gamma 2 (PLCG2) gene might be associated with a spectrum of diseases, ranging from allergy and immunodeficiency to autoimmunity and autoinflammation." (PMID 35955991, 2022). "Together, our results outline a new signaling pathway in B-lymphocytes including the autoimmunity associated genes BANK1, PLCg2 and BLK and they fill a gap in our understanding of the mechanistic relation between associated alleles in human autoimmune diseases and B-cell physiology in particular." (PMID 23555801, 2013).
Immunodeficiency (13 papers, 2014 to 2025). Failure of the immune system to protect the body adequately from infection, due to the absence or insufficiency of some component process or substance. "Autoinflammatory illnesses, antibody deficits, immunodeficiency, and familial cold autoinflammatory syndromes are some of the conditions associated with PLCG2." (PMID 40901642, 2025). "By contrast, monoallelic PLCG2 mutations are associated with variable humoral immune deficiency and immune dysregulation in PLAID and APLAID syndromes." (PMID 32671674, 2020). "Phospholipase Cγ2 (PLCγ2), encoded by PLCG2, is associated with human urticaria, immunodeficiency, and autoimmune diseases." (PMID 36672927, 2023). "The top hit was an immunodeficiency disease caused by PLCG2, phospholipase C gamma 2, a gene coding for a transmembrane signaling enzyme." (PMID 34379637, 2021). "Since Btk plays an important role in adaptive immunity and mutations in PLCG2 have been associated with immune deficiency, downregulation of these genes could have a negative impact on immune response." (PMID 29188362, 2018). "Phospholipase C gamma 2 (PLCG2) is a transmembrane signalling enzyme that is an important driver of many immunological aetiological diseases, such as inflammation, autoimmune diseases, immunodeficiencies, and allergies, as well as haematological malignancies." (PMID 37226082, 2023).
chronic lymphocytic leukemia (11 papers, 2017 to 2024). "Specifically, the somatic mutations in PLCG1 gene have been linked to angiosarcoma and T-cell lymphomas while somatic mutations in PLCG2 contribute to drug (Ibrutinib) resistance in chronic lymphocytic leukaemia (CLL)." (PMID 31918402, 2020). "PLCG2 is associated with immune responses and PLCG2 mutations have been found in the chronic lymphocytic leukemia patient." (PMID 33140821, 2020). "The single site activating mutation Arg665Trp in PLCγ2 is known to occur in the context of ibrutinib resistance in chronic lymphocytic leukemia." (PMID 29972810, 2018). "The cSH2 mutation Arg665Trp (PLCγ2) occurs in the context of resistance to the Bruton’s tyrosine kinase inhibitor ibrutinib used in chronic lymphocytic leukemia." (PMID 29972810, 2018). "For instance, in chronic lymphocytic leukemia, hypermorphic PLCγ2 mutations are associated with resistance to Bruton’s tyrosine kinase (BTK) inhibition by ibrutinib, which provokes constitutive downstream signaling (e.g., IP3 production and Ca2+ release) and B cell proliferation." (PMID 38811530, 2024). "Interestingly, p.Ala708Pro PLCG2 variant has been also discovered in ibrutinib-resistant chronic lymphocytic leukemia (CLL) in the form of somatic variant." (PMID 32671674, 2020). "In addition to mediating GC resistance in B-ALL, hypermorphic PLCγ2 mutations, which confer constitutive signaling have been shown to similarly induce drug resistance in chronic lymphocytic leukemia in which PLC signaling is important for survival and proliferation." (PMID 38811530, 2024). "Ibrutinib emerged as an important and effective treatment for chronic lymphocytic leukemia (CLL) by inhibiting BTK and thereby blocking the PLCγ2 signaling pathway." (PMID 39494327, 2024).
autoimmune disease (10 papers, 2010 to 2025). A disorder resulting from loss of function or tissue destruction of an organ or multiple organs, arising from humoral or cellular immune responses of the individual to their own tissue constituents. "There are several hypermorphic variants in PLCG2 that have been associated with autoimmune disease and cancer." (PMID 40038760, 2025). "PLCg2 is highly expressed in immune cells including microglia, and gain-of-function mutations in PLCG2 cause autoimmune diseases." (PMID 39090623, 2024). "The first indication of its role in autoimmune disease was revealed in mutagenesis screens in mice, identifying gain-of function mutations in PLCγ2." (PMID 34615897, 2021). "A number of pathogenic mutations in PLCγ2 have emerged that were shown to be implicated in autoimmune disease and cancer." (PMID 34615897, 2021). "Interestingly, a mutation in the PLCG2 gene led to increased activity of PLCG2 and a severe autoimmune disease." (PMID 25993291, 2015). "These PLCγ2 signaling-induced autoimmune diseases produce a range of inflammatory phenotypes in both patients and disease models, typically driven by autoantibodies (with the exception of APLAID) and broad autoimmune cell expansion." (PMID 34157287, 2021). "PLCG2 has already been recognized as an excellent discriminator of RA against other types of arthritis or autoimmune diseases and appears to be significantly upregulated in RA synovial tissue as compared with the normal synovial membrane." (PMID 24690414, 2014). "Since AAA is also an autoimmune disease, one could speculate that the increased levels of PLCG2 seen in the current study contribute to AAA pathophysiology." (PMID 25993291, 2015). "Importantly, the PLCγ2-P522R variant has not been associated with any autoimmune diseases or cancers in previous studies, highlighting its beneficial effects on immune cells." (PMID 40038760, 2025).
Arthritis (9 papers, 2010 to 2025). Inflammation of a joint. "Our in vivo animal studies unequivocally support the importance of PLCγ2 in DCs during the development of an inflammatory response associated with antigen-induced arthritis." (PMID 20111715, 2010). "Moreover, PLCγ2-deficient mouse studies showed that blocking PLCγ2 impedes the early development and function of osteoclasts, thereby preventing bone loss in arthritis." (PMID 34157287, 2021). "Pathogenic B cells which form in the thymocyte-expressed, positive selection–associated 1 KO mice in a collagen-induced arthritis model were impaired in PLCγ2 function, and associated calcium flux, thereby reducing the severity of their disease in comparison with control mice." (PMID 34157287, 2021). "Two independent studies have reported that plcγ2-/- mice are protected from developing arthritis, suggeting a pro-inflammatory role for PLCγ2 in this context." (PMID 40821808, 2025). "Additional studies of IC-induced neutrophil activation suggest that the role of Src-family kinases (and, likely, Syk, and PLCγ2) in arthritis development is likely due to their role in Fc-receptor-induced release of pro-inflammatory mediators from neutrophils." (PMID 25998986, 2015). "In this study we explored the contribution of PLCγ2 in DC functions as well as in the development of a T cell dependent model of arthritis in vivo." (PMID 20111715, 2010). "PLCG2 affects neutrophil chemotaxis and inflammation in arthritis, CYP27A1 may serve as a biomarker for intervertebral disc degeneration, and HLA-DQA1 influences neutrophil-mediated immune processes." (PMID 40096134, 2025). "Thus, deletion of PLCγ2 confers protection against the development of mBSA-induced arthritis due to defective antigen-dependent T cell activation." (PMID 20111715, 2010). "This study demonstrates a critical role for PLCγ2 in eliciting inflammatory responses by regulating actin dynamics in DCs and positions the PLCγ2 pathway as a common orchestrator of bone and immune cell functions during arthritis." (PMID 20111715, 2010).
dementia (8 papers, 2019 to 2024). Loss of intellectual abilities interfering with an individual's social and occupational functions. "The rs72824905 single-nucleotide polymorphism in the PLCG2 gene, encoding the p.P522R residue change in Phospholipase C gamma 2 (PLCγ2), associates with protection against several dementia subtypes and with increased likelihood of longevity." (PMID 37081539, 2023). "Of note, the PLCG2 P522R variant is also associated with a reduced risk for dementia subtypes other than AD, such as Lewy body and frontotemporal dementia, and is positively associated with longevity." (PMID 36147734, 2022). "In line with the protection against AD, the by-proxy analysis showed that PLCG2 variant carriers had a reduced risk of having a parent with dementia, OR = 0.88 (0.81–0.95, p = 1.9 × 10−3)." (PMID 31131421, 2019). "It is tempting to speculate that a reduced PLCγ2 function in brain immune cells might lead to an increased risk of dementia, however convincing data to support this are currently lacking." (PMID 33823896, 2021). "Other NVU cell-type DEGs formed connections with both dementia and AD, including Plcg2 (microglia), Dhcr24 (astrocytes), and Psen1 (neurons)." (PMID 39456952, 2024). "With this in mind, it is important to consider how PLCγ2 function may effect microglial responses in the context of amyloid deposition and other neuroinflammatory components of dementia seen in AD." (PMID 34254352, 2021). "Indeed, the strongest effect of PLCG2 variant was observed in cognitively healthy centenarians, individuals where an absence of dementia and extreme longevity is combined." (PMID 31131421, 2019).
amyloid (6 papers, 2020 to 2025). "Plcg2 expression was increased in the 5xFAD mouse model of amyloid pathology, consistent with our findings in human LOAD." (PMID 35180881, 2022). "The protective effect was more pronounced in MCI patients with low Aβ1-42 levels, suggesting a role of PLCG2 in the response to amyloid pathology." (PMID 35000612, 2022). "Specifically, 5xFAD amyloid pathology mice, we observed a disease progression-dependent increase in Plcg2 expression." (PMID 35180881, 2022). "Adding to the notion that p.Pro522Arg exerts its strongest effect downstream of amyloid pathology, Sierksma and colleagues also found PLCG2 as part of a unique gene expression module specifically responsive to Aβ but not TAU pathology." (PMID 35000612, 2022). "The relationship between amyloid plaques and PLCγ2 expression has been supported by increased levels of PLCγ2 throughout disease progression in well-studied models of amyloid pathology, 5x, FAD, TgCRND8, and App NL-G-F/NL-G-F mice." (PMID 36147734, 2022). "Our data show that p.P522R in PLCG2 reduces AD disease progression by mitigating tau pathology in the presence of amyloid pathology and, as a consequence, maintains cognitive function." (PMID 32166339, 2020). "Furthermore, our analysis showed a disease progression-dependent increase in Plcg2 expression in mice with amyloid pathology." (PMID 35180881, 2022). "From a therapeutic point of view, PLCG2-directed therapeutic approaches might, therefore, offer a novel opportunity to complement drugs directed at amyloid clearance or production by modulating the downstream effects of amyloid pathology mediated by microglia." (PMID 32166339, 2020). "In conclusion, PLCG2 expression is increased in several brain regions in LOAD patients and significantly correlates with brain amyloid burden in LOAD patients and AD model mice." (PMID 35180881, 2022).
frontotemporal dementia (6 papers, 2019 to 2024). Frontotemporal dementia (FTD) comprises a group of neurodegenerative disorders, characterized by progressive changes in behavior, executive dysfunction and language impairment, as a result of degeneration of the medial prefrontal and frontoinsular cortices. "A nonsynonymous variant in PLCG2 is associated with reduced risk of ADD, DLB, and frontotemporal dementia, suggesting a broad influence on the mechanisms of neurodegeneration, most likely neuroinflammation." (PMID 39090623, 2024). "A non-synonymous variant in PLCG2 has been proposed to confer protection from AD, and more recently, DLB and frontotemporal dementia (FTD)." (PMID 31996268, 2020). "In addition to the low frequency, non-synonymous variant in the PLCG2 gene (rs72824905, MAF: 0.6%), which was recently observed to be protective against AD, frontotemporal dementia (FTD) and dementia with Lewy bodies, other variants within this group were previously linked with disease risk factors." (PMID 34992629, 2021).
leukemia (6 papers, 2011 to 2024). A malignant (clonal) hematologic disorder, involving hematopoietic stem cells and characterized by the presence of primitive or atypical myeloid or lymphoid cells in the bone marrow and the blood. "PLCG2 was strongly associated with the development of leukemia, and its activity was a potential biomarker of response in CLL and diffuse large B-cell lymphoma (DLBCL) treatment." (PMID 39494327, 2024). "Interestingly, a previous study has shown that c-Myc induced leukemia/lymphoma is accelerated in PLCγ2 deficient mice (PLCγ2−/−Myc)." (PMID 21818355, 2011). "PLCγ2 signaling has been reported to drive leukemia in some cases." (PMID 39494327, 2024). "These kinases are downstream targets of functional pre‐BCR (B‐cell receptor), a distinctive feature of human TCF3‐PBX1 leukemia, and two of its main targets after pre‐BCR stimulation are CrkL and PLCg2." (PMID 33890726, 2021). "Concomitantly, EC-7072 was able to downregulate the total amount of LYN, PLCγ2 and STAT3 in CLL cells, further reinforcing the broad transcriptional reprogramming of primary leukemia cells from patients with CLL upon exposure to the compound." (PMID 31681329, 2019).
lung cancer (6 papers, 2013 to 2025). A malignant neoplasm involving the lung. "TCGA analysis and immunohistochemistry showed that PLCG2 was highly expressed in lung cancer tissues and tended to be associated with poor outcome." (PMID 37031207, 2023). "Among 63 gene members, phosphatidylinositol 3-kinase (PIK3R5), phospholipase C (PLCG2), and SHC adaptor protein showed strong associations with lung cancer susceptibility in our GWAS." (PMID 23762359, 2013). "Therefore, this study suggested that PLCG2 can exist in the form of eccDNA in lung cancer; furthermore, PLCG2, as an oncogene, can promote NSCLC cell metastasis by enhancing mitochondrial function." (PMID 38662139, 2024). "Thus, we indicated that PLCG2 can exist in the form of eccDNA in lung cancer and found that PLCG2 could promote the metastasis of NSCLC cells by enhancing mitochondrial function as an oncogene." (PMID 37031207, 2023). "PLCγ2 is also potentially involved in a small number of solid cancers such as Wilms' tumor (kidney), osteosarcoma, esophageal squamous cell carcinoma, esophageal adenocarcinoma, cervical adenocarcinoma, Birt-Hogg-Dube tumors, non–small-cell lung cancer, and breast cancer." (PMID 34157287, 2021).
lymphoma (6 papers, 2011 to 2024). A malignant (clonal) proliferation of B- lymphocytes or T- lymphocytes which involves the lymph nodes, bone marrow and/or extranodal sites. "This lack of cytotoxicity in the absence of PLCγ2 in NK cells resulted in the failure of NK cell–mediated rejection of major histocompatibility complex I–negative lymphoma cells and NK cell–mediated control CMV infection in vivo." (PMID 34157287, 2021). "While the absence of PLCγ2 can further enable lymphogenesis in certain murine lymphomas, in humans, PLCγ2 signaling can drive leukemogenesis in some cases." (PMID 34157287, 2021). "Phosphorylation of Btk and PLCγ2 was similarly inhibited by ibrutinib in both sensitive cell line SU-DHL-16 and not-sensitive cell line OCI-Ly7, which suggested that ibrutinib induced the anti-lymphoma effect on GCB-DLBCL cell lines through the inhibition of BCR signal pathway." (PMID 24693884, 2014). "Here we validated PLAIDOH’s functional predictions for RP11-960 L18.1, confirming that it is not a cis-regulatory lncRNA for PLCG2, but rather likely acts in the cytoplasm by interacting with one or more RBPs (NF90, KHDRBS1, PUM2) to promote the growth of lymphoma cells." (PMID 30767760, 2019).
small cell lung carcinoma (6 papers, 2019 to 2024). Small cell lung cancer (SCLC) is a highly aggressive malignant neoplasm, accounting for 10-15% of lung cancer cases, characterized byrapid growth, and early metastasis. "A previous study showed that PLCG2 had high expression in small cell lung cancer (SCLC) and was associated with increased stem-like and pro-metastatic potential and reduced overall survival in patients, so we suspected that PLCG2 plays an oncogenic role in NSCLC." (PMID 37031207, 2023). "For example, small cell lung cancer cells with PLCG2-high phenotype had stem-like and pro-metastatic features." (PMID 37377935, 2023). "Moreover, the profibrotic and immunosuppressive monocyte/macrophage population (CD14+CD16+CD81+) was identified in SCLC (small cell lung cancer) tumors, related to PLCG2-high SCLC phenotype with stem-like and pro-metastatic features." (PMID 37483625, 2023). "Treatment strategies could be adjusted for tumors displaying rare recruitment profiles, such as the highly ranked recruitment of PLCG2 predicted for the non-small cell lung cancer H460." (PMID 30653502, 2019).